BTN2A1 (butyrophilin subfamily 2 member A1)
Synonyms: BT2.1; BTF1; BTN2.1; BK14H9.1; DJ3E1.1
Tractability: Small molecule: a structure with a bound ligand is known. Antibody: its Gene Ontology location is reachable by antibodies, with high confidence; UniProt predicts a signal peptide or a membrane-spanning region; the Human Protein Atlas places it where antibodies can reach. PROTAC: ubiquitination databases record sites on it; its protein half-life has been measured.
Gene: Protein-coding gene on chromosome 6 (26,457,904 to 26,476,621, forward strand). Ensembl gene ENSG00000112763.
Subcellular location: Membrane
Subcellular location (Human Protein Atlas): Plasma membrane
Pathways (Reactome):
Immune System: Butyrophilin (BTN) family interactions
Gene Ontology:
Molecular function: signaling receptor binding
Biological process: lipid metabolic process; regulation of cytokine production; T cell receptor signaling pathway
Cellular component: external side of plasma membrane; plasma membrane; membrane
Genetic constraint (gnomAD): Loss-of-function variants: 41 observed, 36.42 expected, observed/expected ratio (o/e) 1.13, 90% interval 0.88 to 1.46. The upper end of that interval is the gene's LOEUF score, 1.46, which puts it in group 6 of 6, group 1 being the genes least tolerant of losing a copy. Missense variants: 642 observed, 693.17 expected, observed/expected ratio (o/e) 0.93, 90% interval 0.87 to 0.99. Synonymous variants: 267 observed, 270.93 expected, observed/expected ratio (o/e) 0.99, 90% interval 0.89 to 1.09.
Homologues: Orthologues: chimpanzee BTN2A1 (99% identical), tropical clawed frog btn1a1l (28% identical), zebrafish cabz01076234.2 (24% identical), tropical clawed frog btn1a1 (22% identical), tropical clawed frog btn2a2 (18% identical), tropical clawed frog btnl8 (17% identical), tropical clawed frog btnl2 (16% identical), zebrafish si:cabz01076234.3 (15% identical), tropical clawed frog btn2a1 (14% identical), zebrafish zgc:123297 (14% identical), zebrafish zgc:162154 (13% identical), zebrafish si:dkey-208m12.2 (8% identical). Paralogues in human: BTN2A2 (82% identical), BTN1A1 (45% identical), BTN3A3 (44% identical), BTN3A1 (41% identical), BTNL9 (38% identical), ERMAP (31% identical), BTNL3 (31% identical), BTNL8 (29% identical), BTNL2 (26% identical), BTN3A2 (25% identical), MOG (14% identical), CD276 (13% identical), and 3 more.
Diseases named in the same sentence as BTN2A1 in open-access papers:
BTN2A1 is named in the same sentence as 45 diseases in open-access papers, as found by Europe PMC text mining. Sharing a sentence is not in itself a finding about the gene and the disease. The quoted sentences say what the papers report.
myocardial infarction (4 papers, 2014 to 2018). Gross necrosis of the myocardium, as a result of interruption of the blood supply to the area, as in coronary thrombosis. "In fact, in these studies, the C-T polymorphism of the BTN2A1 gene allele was significantly associated with the myocardial infarction, dislipidema, chronic kidney diseases (CKD), hypertension, type 2 diabetes mellitus, and metabolic syndrome in Japanese individuals and in East Asian populations." (PMID 29401697, 2018).
breast carcinoma (3 papers, 2020 to 2024). "Decreased levels of CASP8, DDX58, CPNE1, ULK3, PARK7, and BTN2A1, as well as increased levels of TNFRSF9, TNXB, DNPH1, and TLR1, were linked to an elevated risk of breast cancer." (PMID 39351539, 2024).
schizophrenia (3 papers, 2018 to 2021). A major psychotic disorder characterized by abnormalities in the perception or expression of reality. "These include ATP13A1 with BMI, ERAP2 for both inflammatory bowel disease and celiac disease, RPS26 for both type 1 diabetes and rheumatoid arthritis, and BTN2A1 with schizophrenia." (PMID 30061686, 2018). "We found that OCR SNPs on Chromosome 6 were not only in strong LD with schizophrenia and bipolar disorder GWAS index SNPs, but also with the most significant eQTL for three transcripts of the BTN2A1, ZSCAN12P1, and H4C13 genes (r2 with the top eQTL of between .88 and 1) in fetal brain." (PMID 34632689, 2021).
dyslipidemia (2 papers, 2015 to 2018). "In previous studies of ours, we demonstrated that rs6929846 of BTN2A1 was significantly associated with dyslipidemia and CKD in cross-sectional studies of different hospital-based populations." (PMID 25813695, 2015). "The results of the present longitudinal population-based study are thus consistent with these previous observations and validate the association of rs6929846 of BTN2A1 with dyslipidemia and CKD." (PMID 25813695, 2015).
Hypertension (2 papers, 2015 to 2018). The presence of chronic increased pressure in the systemic arterial system. "In this study, we demonstrated that rs6929846 of BTN2A1 was significantly associated with hypertension, with the minor T allele representing a risk factor for this condition." (PMID 25813534, 2015). "The results of the present longitudinal population-based study are thus consistent with these previous observations and validate the association of rs6929846 of BTN2A1 with hypertension." (PMID 25813534, 2015). "We have previously reported that rs6929846 of BTN2A1 is significantly associated with hypertension in a cross-sectional study of a different hospital-based population." (PMID 25813534, 2015). "ii) It is possible that rs6929846 of BTN2A1 is in linkage disequilibrium with other polymorphisms in BTN2A1 or in nearby genes that are actually responsible for the development of hypertension." (PMID 25813534, 2015). "In conclusion, the present results suggest that BTN2A1 is a susceptibility gene for essential hypertension in Japanese individuals." (PMID 25813534, 2015). "In this study, we demonstrated that rs6929846 (T→C) of BTN2A1 was significantly associated with the prevalence of hypertension and also with systolic, diastolic, and mean BP in community-dwelling Japanese individuals, with the minor T allele representing a risk factor for hypertension." (PMID 25813534, 2015). "iii) The functional relevance of rs6929846 of BTN2A1 to the pathogenesis of hypertension remains unclear." (PMID 25813534, 2015).
ovarian carcinoma (2 papers, 2023 to 2024). A malignant neoplasm originating from the surface ovarian epithelium. "Targeting BTN3A1 with novel human antibodies that promote the formation of a complex of this butyrophilin with BTN2A1 elicited coordinated αβ and Vγ9Vδ2 T cell responses against established ovarian cancer xenografts, including orthotopic tumors." (PMID 38541651, 2024). "There are articles linking BTN2A1 to poor prognosis for renal cell carcinoma and ovarian cancer." (PMID 37462769, 2023). "Together, αβ and γδ T cells elicited superior control of established ovarian cancer xenografts in response to these BTN3A1 antibodies, in a manner that was superior to PD-1 checkpoint therapy and dependent on the expression of a second butyrophilin (BTN2A1)." (PMID 38541651, 2024).
abdominal hernia (1 paper, 2022). "To our knowledge, this study also represents the first GWAS of hiatus hernia in which we identified eight susceptibility loci of which four loci (2p16.1 (EFEMP1), 6p22.2 (BTN2A1), 7q33 (CALD1), 11p13 (WT1) are known to correlate with abdominal hernia." (PMID 36584111, 2022).
Anxiety (1 paper, 2025). Intense feelings of nervousness, tension, or panic often arise in response to interpersonal stresses. "On the contrary, we found that BTN2A1 was associated with decreased risk of AD, anxiety, and SCZ, which is consistent with a report that BTN2A1 is involved in the immunomodulation of the activity of γδ T-cells and has significant anti-neuroinflammatory and neuroprotective effects." (PMID 40456753, 2025).
autoimmune disease (1 paper, 2023). A disorder resulting from loss of function or tissue destruction of an organ or multiple organs, arising from humoral or cellular immune responses of the individual to their own tissue constituents. "Selectively blocking BTN3A1’s binding to BTN2A1 may enable selective inhibition of aberrant Vγ9Vδ2 T cell activation in autoimmune diseases." (PMID 37674084, 2023).
gastric cancer (1 paper, 2024). A primary or metastatic malignant neoplasm involving the stomach. "To investigate this possibility, we first overexpressed BRRF1 in EBV-infected cell lines (HK1-EBV and HONE1-EBV), clinically derived NPC cell lines (C666-1 and NPC43), and gastric cancer cell lines (AGS, NCC-24 and SNU719), and detected the gene expression of BTN2A1 and BTN3A1, via RT–qPCR." (PMID 39769218, 2024).
glioma (1 paper, 2023). A benign or malignant brain and spinal cord tumor that arises from glial cells (astrocytes, oligodendrocytes, ependymal cells). "Although Vγ9Vδ2 T cells derived from human PBMCs demonstrated good cytotoxicity against gliomas that overexpress BTN2A1/BTN3A1, such overexpression occurred in less than 30% of GBM cases." (PMID 37770968, 2023). "In conclusion, the high expression of BTN2A1/BTN3A1 may serve as a potential indicator for pre-screening Vγ9Vδ2 T cells derived from healthy human PBMCs for glioma treatment." (PMID 37770968, 2023). "The SAT group exhibits elevated protein expression of BTN2A1 and BTN3A1, accompanied by differential gene expression related to lipid metabolism and glioma inflammatory response pathways." (PMID 37770968, 2023). "Protein expression of BTN2A1 and BTN3A1, along with gene expression related to lipid metabolism and glioma inflammatory response pathways, is analyzed in matched tumor tissue samples." (PMID 37770968, 2023).
HCMV infection (1 paper, 2015). "Real-time PCR measurements from cell lysates along HCMV infection supported elevation in BTN2A1 and IGSF8 mRNA levels." (PMID 26599541, 2015). "These experiments demonstrated that BTN2A1 and IGSF8 are targeted for degradation since their protein levels were downregulated during HCMV infection, whereas the levels of the GFP which was expressed from the same transcript was elevated." (PMID 26599541, 2015). "We reveal here that BTN2A1 and IGSF8, members of the Ig superfamily, are degraded during HCMV infection." (PMID 26599541, 2015). "We show that BTN2A1 and IGSF8, two cell surface proteins that belong to the immunoglobulin (Ig) superfamily are degraded during HCMV infection." (PMID 26599541, 2015).
head and neck cancer (1 paper, 2020). A primary or metastatic malignant neoplasm affecting the head and neck. "BTN2A1 and BTN3As might be the direct ligands that activate γδ T cells in head and neck cancers." (PMID 33101298, 2020).
hypertriglyceridemia (1 paper, 2015). A laboratory test result indicating elevated triglyceride concentration in the blood. "The rs6929846 (T→C) SNP of the butyrophilin, subfamily 2, member A1 gene (BTN2A1) was found to be significantly associated with the prevalence of both hypertriglyceridemia (dominant model) and hyper-LDL cholesterolemia (dominant and recessive models)." (PMID 25813695, 2015). "In conclusion, the results from the present study suggest that BTN2A1 is a susceptibility gene for hypertriglyceridemia, hyper-LDL cholesterolemia and CKD in community-dwelling Japanese individuals." (PMID 25813695, 2015). "BTN2A1 may thus be a susceptibility gene for hypertriglyceridemia, hyper-LDL cholesterolemia and CKD in Japanese individuals." (PMID 25813695, 2015). "The prevalence of hypertriglyceridemia or hyper-LDL cholesterolemia was greater in the combined group of subjects with the CT or TT genotypes of rs6929846 of BTN2A1 than in the subjects with the CC genotype from 40 to 90 years of age." (PMID 25813695, 2015).
kidney stone (1 paper, 2025). "Five of these protein ratio pairs positively promote kidney stone development: BAIAP2/MME protein level ratio, GRPEL1/MME protein level ratio, HLAE/IL15 protein level ratio, CEACAM1/GGT1 protein level ratio and BTN2A1/IL18BP protein level ratio." (PMID 40673688, 2025).
mesothelioma (1 paper, 2023). A usually malignant and aggressive neoplasm of the mesothelium which is often associated with exposure to asbestos. "As the results suggest that Vδ2 T cells have certain effectiveness against mesothelioma, we next examined the expression of BTN2A1, BTN3A1, and PD-L1 in mesothelioma tumor tissue sections obtained from the mice experiments described earlier, at the time of death between 17-21 days." (PMID 38077396, 2023). "Therefore, our analysis reveals that the expression of BTN2A1/BTN3A1 is low on the tumor cells in mesothelioma, where a high percentage of cells express PD-L1/PD-L2, which could hinder the effectiveness of Vδ2 T cells for immunotherapy." (PMID 38077396, 2023). "Flow cytometry was used to examine expression of BTN2A1, BTN3A1, PD-L1, PD-L2 on mesothelioma cell lines." (PMID 38077396, 2023).
nasopharyngeal carcinoma (1 paper, 2024). A carcinoma arising from the nasopharyngeal epithelium. "Interestingly, Liu and colleagues observed NLRC5-mediated transactivation of endogenous BTN2A1 only upon EBV-reactivation, which also leads to IFNγ upregulation in nasopharyngeal carcinoma cells." (PMID 39035010, 2024).
prostate tumors (1 paper, 2023). "In our analysis of the SU2C/PCF Dream Team dataset, we found BTN3A1 and BTN2A1 transcripts to be expressed in bone metastatic tumors at similar levels to prostate tumors and soft tissue metastases to the liver and lymph nodes." (PMID 37134157, 2023).
tumor (29 papers, 2020 to 2026). "In particular, engagement of BTN2A1 expressed on M2-polarized macrophages and tumor-associated macrophages (TAMs) via a specific antibody promotes their reprogramming into M1-polarized macrophages through the SYK and MAPK signaling pathways." (PMID 41596393, 2026). "Subsequently, the germline-encoded regions of the TCR Vγ9 chain directly bind to BTN2A1 on tumor cells, then leads to Vγ9Vδ2+ T Cell activation." (PMID 36685942, 2022). "Subsequently, the germline-encoded regions of the TCR Vγ9 chain directly bind to BTN2A1 on tumor cells, as described by us and confirmed later by others." (PMID 35880177, 2022). "As a result, IL-22 is potentiated to activate the downstream JAK3-STAT3 pathway to achieve a greater expression of BTN2A1 on the NPC tumor cells." (PMID 39769218, 2024). "Elevated expression of BTN3A1 in tumor cells regulated by the mevalonate pathway facilitates the recruitment of BTN2A1 thereby activating the Vγ9Vδ2 T cells." (PMID 39624111, 2024). "Overall, this study demonstrated that Vδ2 T cells can successfully inhibit NPC tumor growth when the hurdle of sufficient BTN2A1/BTN3A1 expression are overcame by use of the EBV-reactivating agent (L2)P4." (PMID 36632221, 2023). "Vδ2 T cells are activated by recognition of phosphoantigens (pAgs) presented by BTN2A1/BTN3A1 on the tumor cells 26-28." (PMID 36632221, 2023). "Recent findings indicated that Vγ9Vδ2 TCR senses the intracellular accumulation of phosphoantigen (pAg) bound with the BTN2A1/3A1 complex in cancer cells and activates the anti-tumor response of γδ2 T cells." (PMID 37835538, 2023). "While not directly measured in our study, it can be assumed that HPV+ and cancer organoids produce increased amounts of endogenous pAg isopentenyl pyrophosphate (IPP), leading to BTN2A1/3A1-dependent γδ T cell activation and subsequent tumour cell killing." (PMID 38090581, 2023). "Since Vγ9Vδ2 T cells can recognize tumor cells expressing BTN2A1 and BTN3A1, we compared the expression of these two molecules in different GBM cell lines by flow cytometry and matched tumor samples of PTCs using IHC staining." (PMID 37770968, 2023). "IHC staining conducted on matched tumor tissue samples from PTCs in the SAT group confirmed the elevated expression levels of BTN2A1 and BTN3A1." (PMID 37770968, 2023). "Immunofluorescence of the tumor section confirmed infiltration of Vδ2 T cells into the tumor, especially to cells with BTN2A1 expression (a Vδ2 T cell activating molecule) despite PD-L1 co-localization." (PMID 38077396, 2023). "(L2)P4 reactivates latent EBV, which increased BTN2A1 and BTN3A1 expression and conferred higher susceptibility towards Vδ2 T cells cytotoxicity in vitro, as well as enhanced tumor regression in vivo by adoptive transfer of Vδ2 T cells." (PMID 36632221, 2023). "The increased P4-induced BTN2A1/BTN3A1 expression possibly triggered higher activation of the infiltrated Vδ2 T cells for cytotoxicity that lead to tumor regression as observed." (PMID 36632221, 2023). "To further illustrate the characteristics of the tumor cells in the microenvironment, we quantified the cells expressing combinations of BTN2A1, PD-L1, and/or PD-L2 in the tile scan of the tumor section from the two-dose treatment (Supplementary 5B)." (PMID 38077396, 2023). "The JAK3-STAT3 pathway could act in concordance with IL-22 to enhance the expression of BTN2A1, which likely leads to increased tumor cell killing by Vγ9Vδ2 T cells for enhanced potential as immunotherapy against the cancer." (PMID 39769218, 2024). "BTN2A1 is an important molecule in activating the function of Vγ9Vδ2 T cells against tumor cells." (PMID 39769218, 2024). "However, when IL-22-producing Th17, NKT, and Th22 cells infiltrate into the tumor, the increased amount of IL-22 can possibly offset the effect of BTN2A1 and Vγ9Vδ2 T cells, which eventually leads to tumor progression." (PMID 39769218, 2024).